ESR2 (estrogen receptor 2)
Diseases named in the same sentence as ESR2 in open-access papers (continued):
Sharing a sentence is not in itself a finding about the gene and the disease.
breast cancer (continued). "A cohort study was conducted to examine the role of genetic polymorphisms in three estrogen metabolizing enzymes (COMT, CYP1A1, CYP1B1) and the two estrogen receptors (ESR1, ESR2) in the progression of benign breast disease (BBD) to breast cancer." (PMID 16808847, 2006). "Conversely, ERβ, encoded by the ESR2 gene, is the most abundantly expressed estrogen receptor in normal mammary glands and has shown conflicting roles in breast cancer, with some in vitro studies suggesting its inhibitory effects on cancer cell progression and invasion." (PMID 41200178, 2025). "However, breast cancer patients undergoing systemic treatment demonstrate decreased disease‐free survival when their tumors show elevated expression of the ESR2." (PMID 39285617, 2025). "Moreover, the GOBO analysis shows an elevated expression profile of the PTGS2/ESR2/EGFR/JUN/MMP2 genes’ signature in the most aggressive breast cancer subtype (Basal) in breast tumor samples and breast cancer cell lines." (PMID 39707884, 2024). "This could be ascribed to their interaction with various breast cancer-associated protein targets such as CAs, AKR1B1, ADORA3, PTPN1, ESR2, and EGFR." (PMID 39482666, 2024). "Finally, through in silico studies, we identified specific biomarkers, including TOMM20, NFE2L2, CAT, and ESR2, correlated with poor prognosis in luminal breast cancer." (PMID 39767718, 2024). "Therefore, miR-let-7c was inversely related to ESR2 expression, consistent with previous studies on breast cancer stem cells." (PMID 38254383, 2024). "Additionally, the mRNA expression of both estrogen receptor alpha (ESR1) and beta (ESR2) was analyzed to further understand the differential response of luminal breast cancer cell lines with distinct basal levels of ESR2 expression." (PMID 39767718, 2024). "Interestingly, when LINC00052 expression is inhibited, ‘Pro-oncogenic action of estradiol_estrogen receptors’ as well as ‘ESR1/ESR2 ratio in breast cancer’ signalling pathways are modulated." (PMID 38832821, 2024). "Furthermore, patients with Basal and Luminal A breast cancer had a positive correlation between the expression of the ESR2 gene and SLIT2, presenting a new possible field to explore as a marker." (PMID 39596804, 2024). "However, the MAP1B and ESR2 gene expression levels were positively correlated in Luminal A breast cancer patients." (PMID 39596804, 2024). "Herein, we introduce the functional role of ERβ suppression following isolation of monoclonal cell populations of MDA-MB-231 breast cancer cells transfected with shRNA against human ESR2 that permanently resulted in 90% reduction of ERβ mRNA and protein levels." (PMID 35719919, 2022). "Furthermore, we recently demonstrated that estrogen suppresses PAOX expression in an ESR2-dependent manner in MCF-7 breast cancer cells." (PMID 36142401, 2022). "Hence, the involvement and importance of ERβ (ESR2) in breast cancer remains controversial; moreover, most studies have been focused on measuring ERβ protein levels." (PMID 35304506, 2022). "Barh demonstrated that in silico analysis, apart from repressing HMGA2, RAS, and MYC, let-7 may also target CYP19A1, ESR1, and ESR2, thereby potentially blocking estrogen signaling in ER-positive breast cancers." (PMID 34442460, 2021). "EO771 mouse mammary tumor cells originated from a spontaneous ER+ mammary tumor in a C57BL/6 mouse have been used as allografts for luminal B disease given their expression of ESR2 (ERβ), although these cells also have been classified as basal-like." (PMID 34532657, 2021). "This suggests that genistein may have the potential to elicit counterproductive effects in women already being treated for a high ESR1/ESR2 ratio breast cancer using these common over-the-counter therapeutics." (PMID 34578926, 2021). "Similarly, as novel breast cancer susceptibility genes, we found AKT1, ESR2, and RAD50 as the top genes." (PMID 33376724, 2020).
breast cancer (continued). "Recent studies have verified tissues ESR1 mutations in most tumor patients, especially with metastatic breast cancer, and some of them to activate the estrogen‐independent receptor, whereas ESR1 and ESR2 expression not only express in breast cancer but also have been shown in other cancer types." (PMID 32536040, 2020). "Therefore, the objective of the present study was to investigate the association between certain ESR1, ESR2, HER2, UGT1A4, and UGT2B7 single nucleotide polymorphisms and breast cancer." (PMID 31888550, 2019). "The human ESR2 gene (estrogen receptor β) promoter contains a known SNP marker (rs35036378) of a primary ESR2-deficient pT1 tumor whose development can lead to breast cancer without proper preventive treatment." (PMID 28105927, 2016). "(estrogen receptor β) contains the SNP marker (rs35036378) of a primary ESR2-deficient pT1 tumor that can transform into breast cancer without preventive treatment." (PMID 26694100, 2015). "For example, the androgen (AR) and estrogen (both ESR1 and ESR2) nuclear hormone receptors are known to be relevant in prostate and breast cancers, and the alpha-type platelet-derived (PDGFRA) and epidermal (EGFR) growth factor receptors are recognised angiogenesis factors." (PMID 22558171, 2012). "Genetic variants in hormone receptor genes may be crucial predisposing factors for breast cancer, and microsatellites in the estrogen receptor (ESR1, ESR2) and androgen receptor (AR) genes have been suggested to play a role." (PMID 22792352, 2012). "In our in silico analysis, we recently showed that, apart from repressing MYC, ras, and HMGA2, let-7 may also target CYP19A1, ESR1, and ESR2, thereby potentially blocking estrogen signalling in er-positive breast cancers." (PMID 20179807, 2010). "Taken together, the increased expression of ESR2, combined with the reduced expression of key mitochondrial and antioxidant regulators, suggests that obesity-related inflammation enhances the aggressive phenotype of luminal breast cancer through a compromised mitochondrial and antioxidant response." (PMID 39767718, 2024). "Thus, the coexpression status of MET and ESR2 could predict a response to treatment in patients with breast cancer." (PMID 39742369, 2024). "The function of ERβ (ESR2 gene) in breast cancer progression is largely unknown." (PMID 37711895, 2023). "We hypothesized that the ERβ/ESR2 mRNA expression levels in ERα+ human breast cancer samples would negatively correlate with those of genes with promoters that contain ERE-AP1 response elements and that there would be a positive association between ESR2 mRNA expression levels and overall survival." (PMID 35574319, 2022). "We found that ESR2 mRNA is not abundantly expressed in primary breast cancer, but that higher ESR2 expression is found particularly within ERα-negative breast cancer subtypes and that ESR2-high has a significant association to survival in endocrine-treated patients as well as patients with TNBC." (PMID 35304506, 2022). "Furthermore, analysis of publicly available breast cancer-related patient survival datasets shows that higher ESR2 expression levels correlate with longer patient survival, but the correlation is only significant in tumors with relatively abundant tumor-infiltrating CD8+ T cells." (PMID 33462142, 2021). "Additionally, we further explored the relative gene expression of other important hormonal receptors in breast cancer, such as estrogen receptor beta (ESR2), progesterone receptor (PGR) and androgen receptor (AR), concomitantly with estrogen receptor alpha (ESR1)." (PMID 31817155, 2019). "Among which, ESR2 was shown to be involved in the estrogen and prolactin signaling pathways and may take a significant role in the effect of germacrone, curdione, and furanodiene in the treatment of breast cancers and should be studied in animal models." (PMID 29138518, 2017).
breast cancer (continued). "Pan-cancer analysis revealed a negative correlation between the expression of STAT3, VEGFA, ESR2, and ABCG2 and breast cancer patient survival." (PMID 41121538, 2025). "For this purpose, we used the Gene expression-based Outcome for Breast Cancer Online (GOBO) dataset that contains data about 1881 breast cancer patients to produce a gene set composed of PTGS2/ESR2/EGFR/JUN/ MMP2 genes’ signature." (PMID 39707884, 2024). "The current analysis further certifies the decisive engrossment of PTGS2/ESR2/EGFR/JUN/MMP2 genes’ signature and some interactor proteins in promoting breast cancer development." (PMID 39707884, 2024). "To further dissect the biological contributions of the selected PTGS2/ESR2/EGFR/JUN/and MMP2 genes in breast cancer development, we studied their correlation, as a group, to different breast cancer molecular subtypes and ER / HR status." (PMID 39707884, 2024). "Similar results were obtained when examining the co-expression of PTGS2/ESR2/EGFR/JUN/and MMP2 genes’ signature in breast cancer cell lines representative of different molecular subtypes." (PMID 39707884, 2024). "These include PTGS2, EGFR, ESR2, MMP2, JUN, and HSP90AB1, which all revealed the highest mRNA expression level in the basal breast cancer subtype, thus proposing a potential similar engagement of these genes in the pathogenesis of the basal subtype." (PMID 39707884, 2024). "Combining the results of network pharmacology with other bioinformatics databases suggests that myrrh’s active components exert anti-cancer effects by regulating genes involved in breast cancer pathogenesis, particularly PTGS2, EGFR, ESR2, MMP2, and JUN." (PMID 39707884, 2024). "The estrogen signalling pathway leads to the over-expression of Estrogen receptors (ESR1 and ESR2), and the over-expression of Progesterone receptors (PGR) genes are involved in luminal A breast cancer." (PMID 37629702, 2023). "In the TCGA breast cancer cohort, most of the BMPs were significantly correlated with ESR1 (ERα) and ESR2 (ERβ) with a contrasting pattern." (PMID 37333824, 2023). "A previous study showed that the overexpression of ESR2 can increase the PTEN protein, thereby inhibiting the PI3K/Akt signalling pathway and inhibiting breast cancer cells." (PMID 38256877, 2023). "SELENBP1 interacts with the nuclear receptor estrogen receptor 2 (ESR2, ERβ) to modulate cell proliferation and tumor growth in breast cancer." (PMID 36386843, 2022). "Lastly, ESR2 (ERβ gene) expression was negatively correlated with ESR1 (ERα gene) and CCND1 RNA expression in human metastatic ERα+/HER2- breast cancer samples." (PMID 35574319, 2022). "The present study showed that targets of Chrysanthemum phytochemicals (luteolin, chlorogenic acid, rutin, quercetin, and apigenin) belong to estrogen receptors such as ESR1, ESR2, and PGR and are major therapeutic targets of breast cancer." (PMID 34083561, 2021). "A second isoform of estrogen receptor is also expressed in breast cancer (ER-β/ESR2); however, the relative contributions of ER-β to this disease are less well understood." (PMID 34680352, 2021). "Accordingly, previous studies have demonstrated that drugs targeting ESR1, ESR2, and PGR are effective in the treatment of breast cancer and improve promote clinical outcomes." (PMID 34322374, 2021). "Several targets belong to the estrogen receptor, such as ESR1 (estrogen receptor-α, degree = 5), ESR2 (estrogen receptor-β, degree = 5), and PGR (progesterone receptor, degree = 6), are major therapeutic targets of breast cancer." (PMID 34083561, 2021). "Therefore, the downregulation of ESR1 and PTGS2 and upregulation of ESR2 by AESN might not only provide antitumor effects against ER+ breast cancer but also afford protective effects towards the development and progression of Parkinson’s disease and Alzheimer’s disease." (PMID 31835887, 2019).
breast cancer (continued). "All three EDCs–PCB 153, phthalates, and BPA influenced five common genes—CYP19A1, EGFR, ESR2, FOS, and IGF1—in breast cancer as well as in endometriosis." (PMID 26512648, 2015). "Five genes—CYP19A1, EGFR, ESR2, FOS, and IGF1—were common among all three EDCs–PCBs, phthalates and BPA, 17β-estradiol, breast cancer, and endometriosis." (PMID 26512648, 2015). "Five genes—CYP19A1, EGFR, ESR2, FOS, and IGF1—were common among all three EDCs–PCB 153, phthalates and BPA, breast cancer, and endometriosis." (PMID 26512648, 2015). "This study provides a higher level of evidence that DC-SCRIPT is indeed an independent, pure prognostic, factor for primary breast cancer and shows that DC-SCRIPT mRNA expression is most informative for either ESR1-positive and/or ESR2-low pT1 tumors." (PMID 21122099, 2010). "ESR2 counteracts the activity of ESR1 in many systems and is also expressed in the majority of breast cancers." (PMID 21122099, 2010). "ESR2 mRNA levels (p = 2.5 × 10−8) were significantly higher in breast cancer patients who did not achieve a pCR following chemotherapy." (PMID 39767718, 2024). "Early studies on breast cancer tissues demonstrated a high level of ESR2 promoter methylation, leading to the down-regulation or loss of ERβ expression in invasive breast cancer, but not in the normal mammary gland." (PMID 39796024, 2024). "Both the TNBC lines had a significantly higher expression of full-length ESR2 compared with MCF10A (MDA-MB-231: 4.4-fold, p < 0.05; MDA-MB-468: 5.2-fold, p < 0.01), and these levels were comparable to those in the ERα+ MCF7 and T47D breast cancer cell lines." (PMID 35574319, 2022). "Consistently, an immune genetic profiling study found a negative correlation between TILs and ESR1/ESR2 expression ratio in luminal breast cancer." (PMID 35008370, 2021). "Taken in context, this suggests that a genistein-supplemented regimen for treating breast cancer can be beneficial; however, it might be contraindicated for women whose tumors present with a high ESR1/ESR2 ratio." (PMID 34578926, 2021). "In addition to breast cancer, ESR1, ESR2, and PGR also mediate the progression of prostate cancer, colon cancer, ovarian cancer, and lung cancer." (PMID 34322374, 2021). "In contrast, ESR2 seems to be a tumor suppressor gene, which is not expressed in early stages of breast cancer." (PMID 34322374, 2021). "The present study provides methylation levels for the promoters of APC, BRCA1, CDKN2A, ESR1, ESR2, HER2/neu and PTEN, CDKN2A exon 2 and LINE-1 in tumor, tumor-adjacent and tumor-distant tissues from 18 breast cancer patients and normal breast tissues from four healthy women." (PMID 28403857, 2017). "To provide a higher level of evidence for DC-SCRIPT mRNA expression as a prognostic marker, we now report on DC-SCRIPT expression and its significance in a retrospective validation study of 1,505 breast cancer patients with known ESR1, ESR2, and PGR expression levels." (PMID 21122099, 2010). "Notably, ESR2 expression levels in clone shERβ MDA-MB-231 cells seem to resemble ERα-positive and ERβ-negative MCF-7 breast cancer cells." (PMID 35719919, 2022). "To date, neither ESR2 nor AR genes has been identified by breast cancer GWAS." (PMID 22792352, 2012).
breast cancer (continued). "Unraveling the precise role of DC-SCRIPT in the complex genomic and non-genomic interplay between ESR1, ESR2, and their isoforms might turn out to be rewarding for elucidating the 'yin-yang' role of these factors in breast cancer." (PMID 21122099, 2010). "In conclusion, our findings indicate that markers including ESR2, TOMM20, NFE2L2, and CAT not only play a role in mitochondrial oxidative stress but may also influence drug response and cancer recurrence, making them promising biomarkers to predict prognosis in luminal breast cancer." (PMID 39767718, 2024). "The analysis of clinical data indicated that the correlation between the expressions of ADAM12 and ESR1 in patients with Luminal A and Luminal B breast cancer was negative; however, the expressions of ADAM12 and ESR2 were not statistically significant." (PMID 39596804, 2024). "In addition to classical nuclear ERα (ESR1) and ERβ (ESR2) acting as ligand-activated transcription factors, it has become evident that non-nuclear ERs govern numerous cell processes in the brain and exert beneficial cardiometabolic effects without uterine or breast cancer growth in mammals." (PMID 33025361, 2020). "Furthermore, an association with various estrogen-dependent genes such as ANXA1, PIWIL2, CASP4, ESR1/ESR2, PLAC1, and SOCS2, has been shown in breast cancer—however, up to date, no such data concerning adenocarcinomas of the esophagogastric junction have been published." (PMID 31467538, 2019).